ADCY8 (adenylate cyclase 8)
Description:
Catalyzes the formation of cAMP in response to calcium entry leadings to cAMP signaling activation that affect processes suche as synaptic plasticity and insulin secretion. Plays a role in many brain functions, such as learning, memory, drug addiction, and anxiety modulation through regulation of synaptic plasticity by modulating long-term memory and long-term potentiation (LTP) through CREB transcription factor activity modulation. Plays a central role in insulin secretion by controlling glucose homeostasis through glucagon-like peptide 1 and glucose signaling pathway and maintains insulin secretion through calcium-dependent PKA activation leading to vesicle pool replenishment. Also, allows PTGER3 to induce potentiation of PTGER4-mediated PLA2 secretion by switching from a negative to a positive regulation, during the IL1B induced-dedifferentiation of smooth muscle cells.
Synonyms: AC8; HBAC1; ADCY3
Tractability: Small molecule: a high-quality ligand is known. Antibody: its Gene Ontology location is reachable by antibodies, with high confidence; UniProt places it where antibodies can reach, with medium confidence; UniProt predicts a signal peptide or a membrane-spanning region; the Human Protein Atlas places it where antibodies can reach. PROTAC: its protein half-life has been measured; a small molecule that binds it is known.
Target class: Enzyme; Lyase
Gene: Protein-coding gene on chromosome 8 (130,780,300 to 131,041,587, reverse strand). Ensembl gene ENSG00000155897.
Subcellular location: Cell membrane; Basolateral cell membrane; Apical cell membrane; Synapse; Cell projection, dendrite; Cell projection, axon; Presynaptic cell membrane; Postsynaptic density; Membrane raft; Membrane, coated pit; Cytoplasmic vesicle, clathrin-coated vesicle membrane; Membrane, caveola
Subcellular location (Human Protein Atlas): Cytosol; Plasma membrane; Nucleoplasm
Pathways (Reactome):
Signal Transduction: Adenylate cyclase activating pathway; G alpha (i) signalling events; G alpha (s) signalling events; G alpha (z) signalling events; GPER1 signaling; Hedgehog 'off' state; PKA activation
Metabolism: Glucagon signaling in metabolic regulation; Glucagon-like Peptide-1 (GLP1) regulates insulin secretion; PKA activation in glucagon signalling
Disease: ADORA2B mediated anti-inflammatory cytokines production; FCGR3A-mediated IL10 synthesis
Neuronal System: Adenylate cyclase inhibitory pathway; CREB1 phosphorylation through the activation of Adenylate Cyclase
Cellular responses to stimuli: High laminar flow shear stress activates signaling by PIEZO1 and PECAM1:CDH5:KDR in endothelial cells
Transport of small molecules: Vasopressin regulates renal water homeostasis via Aquaporins
Gene Ontology:
Molecular function: actin binding; adenylate cyclase activity; calcium- and calmodulin-responsive adenylate cyclase activity; calmodulin binding; protein dimerization activity; protein heterodimerization activity; protein homodimerization activity; protein phosphatase 2A binding; phosphorus-oxygen lyase activity
Biological process: activation of protein kinase A activity; adenylate cyclase-activating G protein-coupled receptor signaling pathway; cAMP biosynthetic process; cellular response to calcium ion; cellular response to forskolin; cellular response to glucagon stimulus; cellular response to glucose stimulus; cellular response to morphine; G protein-coupled opioid receptor signaling pathway; glucose homeostasis; glucose mediated signaling pathway; learning or memory; locomotory behavior; memory; neuroinflammatory response; positive regulation of cytosolic calcium ion concentration; positive regulation of insulin secretion; positive regulation of insulin secretion involved in cellular response to glucose stimulus; positive regulation of long-term synaptic depression; positive regulation of long-term synaptic potentiation; positive regulation of synaptic plasticity; protein complex oligomerization; protein homooligomerization; regulation of cellular response to stress; regulation of cytosolic calcium ion concentration; and 7 more
Cellular component: actin cytoskeleton; apical plasma membrane; axon; basolateral plasma membrane; caveola; clathrin-coated pit; dendrite; excitatory synapse; membrane; membrane raft; neuronal cell body membrane; plasma membrane; plasma membrane raft; postsynaptic density; presynaptic active zone; presynaptic membrane; synapse; clathrin-coated vesicle membrane
Genetic constraint (gnomAD): Loss-of-function variants: 48 observed, 104.15 expected, observed/expected ratio (o/e) 0.46, 90% interval 0.37 to 0.59. The upper end of that interval is the gene's LOEUF score, 0.59, which puts it in group 2 of 6, group 1 being the genes least tolerant of losing a copy. Missense variants: 1,340 observed, 1,561.5 expected, observed/expected ratio (o/e) 0.86, 90% interval 0.82 to 0.9. Synonymous variants: 651 observed, 640.41 expected, observed/expected ratio (o/e) 1.02, 90% interval 0.95 to 1.09.
Homologues: Orthologues: chimpanzee ADCY8 (99% identical), macaque ADCY8 (99% identical), rabbit ADCY8 (98% identical), guinea pig ADCY8 (98% identical), pig ADCY8 (98% identical), dog ADCY8 (98% identical), mouse Adcy8 (97% identical), rat Adcy8 (97% identical), tropical clawed frog adcy8 (89% identical), zebrafish adcy8 (61% identical). Paralogues in human: ADCY6 (35% identical), ADCY5 (35% identical), ADCY2 (31% identical), ADCY1 (31% identical), ADCY3 (30% identical), ADCY4 (30% identical), ADCY7 (28% identical), ADCY9 (25% identical), GUCY2D (14% identical), GUCY2F (14% identical), NPR1 (13% identical), NPR2 (13% identical), and 5 more.
Diseases named in the same sentence as ADCY8 in open-access papers:
ADCY8 is named in the same sentence as 76 diseases in open-access papers, as found by Europe PMC text mining. Sharing a sentence is not in itself a finding about the gene and the disease. The quoted sentences say what the papers report.
diabetes (14 papers, 2011 to 2025). "These included proteins expressed by pancreatic islet cells (Ptch1, Disp1, Pck1, and Cacna1e) as well as proteins known to be associated with diabetes mellitus susceptibility or glucose metabolism (Adcy8, Perm1, Sorbs1, and Pla2g6)." (PMID 37934865, 2023). "Notably, ADCY8 is significantly reduced in islets from diabetic Goto-Kakizaki (GK) rats or in pancreatic β-cells at glucotoxicity, suggesting that the reduction of ADCY8 is associated with impaired secretory capacity of β-cells in diabetes." (PMID 31485455, 2019).
Anxiety (8 papers, 2016 to 2024). Intense feelings of nervousness, tension, or panic often arise in response to interpersonal stresses. "This gene has been found to regulate short-term plasticity, presynaptic/post-synaptic LTP and anxiety-like behaviors induced by stress, with Adcy8-null mice showing less susceptibility to repeated exposures." (PMID 37653491, 2023). "A recent study found changes in anxiety-like behavior linked to a rodent PTSD-like model accompanied by aberrant Adcy8 expression in the amygdala." (PMID 33192359, 2020). "Further, Adcy8 codes for a protein kinase that has been repeatedly implicated in anxiety-like behavior, synaptic plasticity, and mood disorders." (PMID 33192359, 2020). "A hypothesis emerging from our findings that could be tested in future experiments is that increased expression of Adcy8 in the ACC may be linked to anxiety produced by neuropathic pain." (PMID 35005298, 2022). "In addition, recent human studies suggest that single-nucleotide polymorphism (SNPs) and mutation on ADCY8 gene may link to anxiety or depression." (PMID 27234425, 2016). "A possible interaction of the Adcy8 gene with SNI-induced anxiety could be tested in future studies." (PMID 35005298, 2022).
breast carcinoma (7 papers, 2019 to 2025). "Our research identifies key genes, such as ADCY8, associated with invasive breast cancer and verifies their expression in breast cancer cells." (PMID 40095726, 2025). "This gender‐specific nuance further underscores the substantial role that ADCY8 may play in breast cancer, a disease with a notable female predisposition." (PMID 40095726, 2025). "The protein expression of ADCY8 was found to be higher in breast cancer tissues compared to normal breast tissues, suggesting its potential role in breast cancer progression." (PMID 40095726, 2025). "Additional experiments will help elucidate the functional role of ADCY8 in breast cancer and its potential as a therapeutic target." (PMID 40095726, 2025). "We have uncovered a novel gene, ADCY8, which has been largely overlooked in studies concerning the invasion and metastasis of breast cancer." (PMID 40095726, 2025). "While GPC‐Net successfully identified ADCY8 as a potential biomarker for breast cancer invasion and migration, its specific role in breast cancer metastasis remains to be further validated." (PMID 40095726, 2025). "Further comprehensive functional studies are necessary to fully understand the role of ADCY8 in breast cancer progression." (PMID 40095726, 2025). "We found a significant increase in the mRNA and protein expression of ADCY8 in breast cancer cells compared with normal breast cells, and the expression of ADCY8 is primarily located in the cytoplasmic/membranous region." (PMID 40095726, 2025). "Breast cancer cells and breast adenocarcinoma cells exhibited higher ADCY8 expression compared to normal breast cells, indicating a specific role for ADCY8 in breast cancer cells." (PMID 40095726, 2025). "First, differential methylation of ADCY8 was identified as one of three most informative biomarkers in luminal B breast cancer from a cohort of Russian women." (PMID 33178175, 2020). "Additionally, investigating downstream signaling pathways and interacting partners of ADCY8 in breast cancer cells will provide deeper insights into its biological function." (PMID 40095726, 2025).
glioma (7 papers, 2015 to 2022). A benign or malignant brain and spinal cord tumor that arises from glial cells (astrocytes, oligodendrocytes, ependymal cells). "ADCY8 polymorphisms are accompanied by the risk of glioma (brain tumor) in patients with neurofibromatosis type 1 (NF1), which is sex-specific." (PMID 35832555, 2022). "The cAMP pathway was already found to be associated with cancer, with the overexpression of ADCY3 increasing oncogenic potential in gastric cancer cells and ADCY8 acting itself as a risk modifier in glioma." (PMID 30871259, 2019). "Minor allele variants in adenylate cyclase 8 (AC8) increased the risk for glioma in female patients but decreased risk in male patients." (PMID 25985759, 2015). "Recently, we provided human validation for a cooperating oncogenic role for cAMP in brain tumorigenesis when we found that SNPs in ADCY8 were correlated with glioma (brain tumor) risk in individuals with Neurofibromatosis type 1 (NF1)." (PMID 26283963, 2015). "The number of café-au-lait macules has been found to be influenced by common SNPs, polymorphisms in ADCY8 correlate with glioma risk in a sex-specific manner, and rare germline variants in various genes including ATM have been proposed as candidate modifiers of plexiform neurofibroma." (PMID 36760809, 2022). "Interestingly, polymorphism analysis of gliomas in NF1 patients found correlation between specific polymorphisms in the human adenylate cyclase 8 gene with glioma development in a sex-specific manner." (PMID 26000738, 2015). "Based on these results, we performed a human genome-wide association study and found that polymorphisms in the adenylate cyclase 8 gene were correlated with glioma risk in NF1 but in a sex-specific fashion, elevating risk in females and suppressing risk in males." (PMID 25985759, 2015). "The polymorphism of cAMP synthetase, adenylate cyclase 8 (ADCY8), elevates the glioma risk in NF1 female patients, but reduces it in males." (PMID 34566848, 2021).
bipolar disorder (5 papers, 2011 to 2023). A disorder of the brain that causes unusual shifts in mood, energy, activity levels and the ability to carry out day-to-day tasks. "Genome-wide association study (GWAS) and linkage study identified Adcy1 and Adcy8 as genetic risk factors for schizophrenia and bipolar disorder, respectively." (PMID 37465213, 2023). "A linkage study with microsatellite markers reported an association of bipolar disorder with the genetic loci on chromosome 8q24, which covers three candidate risk genes including Adcy8." (PMID 36188604, 2022). "Two follow-up studies using more SNP (single nucleotide polymorphism) markers revealed a finer mapping of the bipolar disorder-associated region on 8q24 and also suggest Adcy8 as a potential risk gene." (PMID 36188604, 2022). "The overlapping region contains gene ADCY8 (adenylate cyclase 8) that is associated with synaptic plasticity, short-term memory performance and with bipolar disorder." (PMID 23460800, 2013). "Genetic variants of Adcy8 gene, as suggested by the human genetics studies, may be associated with bipolar disorder, schizophrenia, autism spectrum disorder, obsessive-compulsive disorder, and posttraumatic stress disorder." (PMID 36188604, 2022). "The level of Adcy8 mRNA is altered in postmortem brain samples collected from schizophrenia and bipolar disorder patients." (PMID 37465213, 2023). "Brain transcriptome analysis of human postmortem samples has found altered level of Adcy8 transcript in bipolar disorder and schizophrenia." (PMID 36188604, 2022).
mood disorder (5 papers, 2015 to 2023). A cognitive disorder a disturbance in which the person's mood is hypothesized to be the main underlying feature. "Dysregulation of Adcy8 has been associated with neurological disorders such as epilepsy, mood disorders, and neurodegenerative diseases, suggesting its potential as a target for therapeutic interventions." (PMID 38005876, 2023). "Genetic mapping revealed a gene, Adenylyl cyclase 8 (Adcy8), for this sheltering feeding behavior that was associated with mood disorders in humans, reflecting its translational value." (PMID 34630052, 2021). "In previous research, they found that ADCY8 is a susceptibility gene for avoidance behavior on mouse and also found that it indirectly induces the susceptibility on human mood disorders." (PMID 26075260, 2015).
Obesity (5 papers, 2018 to 2024). Accumulation of substantial excess body fat. "A recent genome-wide analysis study identified an association between ADCY8 gene variants, obesity, and abnormal adipose tissue depots." (PMID 32847122, 2020). "Notably, the ADCY8 gene not only exhibits a strong association with human obesity but also enhances carcass quality and meat quality in sheep." (PMID 39080522, 2024). "In conclusion, plasma levels of ADCY8 were found to be elevated in patients with obesity, and even more so in the obese-T2D group." (PMID 32847122, 2020). "In conclusion, the current cross-sectional study demonstrated elevated levels of circulating plasma ADCY8 and cAMP in obesity and T2D." (PMID 32847122, 2020). "Furthermore, increased levels of adenylate cyclase 8 and thus increased cyclic AMP levels are associated with obesity and type 2 diabetes." (PMID 35216316, 2022). "Taken together, we propose that establishing the plasma levels of ADCY8 or cAMP may have direct and relevant implications on patient care and development of obesity and T2D complications." (PMID 32847122, 2020).
autism (3 papers, 2011 to 2023). Persistent deficits in social interaction and communication and interaction as well as a markedly restricted repertoire of activity and interest as well as repetitive patterns of behavior. "MG was also associated with SNPs in the brain- and neuron-specific genes, including cerebellum 4 precursor (CBLN4), potassium channel KCNH5, adenylate cyclase 8 (ADCY8), and autism susceptibility candidate gene AUTS2." (PMID 35711735, 2022).
cervical cancer (3 papers, 2016 to 2021). A primary or metastatic malignant neoplasm involving the cervix. "Besides, the methylation of the ADCY8 gene promoter, which is related to the cytological classification, is considered to be a biomarker of cervical cancer." (PMID 33391431, 2021). "Promoter hypermethylation of ADCY8, CDH8, and ZNF582 was corroborated in five cervical cancer cell lines with two exceptions." (PMID 27651839, 2016). "Promoter methylation of ADCY8, CDH8, and ZNF582 was markedly elevated across all four stages of cervical carcinoma." (PMID 27651839, 2016). "DNA methylation but not acetylation is known to regulate the Adcy-8 promoter activity in peripheral blood monocytes, as well as in high-grade cervical cancers." (PMID 33349332, 2020). "TCGA data for the cervical cancer cohort (N = 231) revealed distinct hypermethylation patterns among ADCY8, ZNF582, and CDH8 for reported and non-reported clinical stages (median β value range, 0.427–0.632)." (PMID 27651839, 2016).
Cognitive impairment (3 papers, 2019 to 2024). Abnormal cognition is characterized by deficits in thinking, reasoning, or remembering. "Among the significantly enriched signaling pathways from KEGG analysis, oxytocin signaling pathway (PATH:04921; Cacng2, Adcy1, Kcnj4, Kcnj9, Adcy8, Pik3cd, Elk1, Adcy4, Camkk2, Cacng7, Nos3, Kcnj2) may play an important role in the sevoflurane-induced cognitive impairment." (PMID 31582589, 2019).
dilated cardiomyopathy (3 papers, 2022 to 2024). Cardiomyopathy which is characterized by dilation and contractile dysfunction of the left and right ventricles. "The remaining pathways were all detected with a predominance of control proteins, such as the Citrate cycle (TCA cycle) (P-value < 0.0001; ACLY, DLST, PDHA1, PDHB), except Dilater cardiomyopathy (DCM) (P-value = 0.0006; ACTB, ADCY8, LOC396781, TPM1)." (PMID 38409238, 2024).
endometrial cancer (3 papers, 2016 to 2021). Primary or metastatic malignant neoplasm involving the endometrium (mucous membrane that lines the endometrial cavity). "For example, ADCY8 hypermethylation and altered expression have been observed in endometrial cancer." (PMID 34017995, 2021). "ADCY8 is a membrane bound enzyme which is differentially expressed in endometrial cancer." (PMID 29740512, 2018). "ADCY8 hypermethylation and altered expression have also been observed in endometrial cancer." (PMID 27651839, 2016).
heart failure (3 papers, 2022 to 2024). Inability of the heart to pump blood at an adequate rate to meet tissue metabolic requirements. "These genes included IRS1 encoding insulin receptor substrate, the major component of insulin signaling, the loss of which leads to heart failure, as well as ADCY8 encoding cAMP producing adenylate cyclase 8, which protects against cardiac stress." (PMID 37110207, 2023).
depression (2 papers, 2016 to 2025). "Here, dysfunctional adenylyl cyclase 8 (Adcy8) is identified as a critical risk factor for the development of depression." (PMID 41387170, 2025).
keloid (2 papers, 2021 to 2025). An irregularly shaped, elevated mark on the skin caused by deposits of excessive amounts of collagen during wound healing. "The mRNA levels of NPY, ADCY8, GNG13 and HTR1A were significantly augmented in keloid compared with normal skin samples ***p < 0.001." (PMID 34600545, 2021). "GNG13, ADCY8, NPY and HTR1A may act as core genes in keloid formation and these core genes establish relationship with SP1 and miRNA (hsa-mir-372, hsa-mir-20, hsa-mir-10b), which may influence multiple signaling pathways in the pathogenesis of keloid." (PMID 34600545, 2021). "Additionally, 14 genes such as GRIN2D, HTR7, and CCKAR were found to be upregulated in the calcium signaling pathway, while 43 genes, including ATP2A1, ADCY8, and MCOLN3, were significantly downregulated, suggesting that calcium signaling plays a critical role in the pathology of keloids." (PMID 41562114, 2025).